CRP (C-reactive protein)
Diseases named in the same sentence as CRP in open-access papers (continued):
Sharing a sentence is not in itself a finding about the gene and the disease.
Thrombocytosis (continued). "Patients with sJIA have a range of other prominent features, including marked elevation of erythrocyte sedimentation rate (ESR) and C-reactive protein (CRP), leucocytosis with high neutrophil counts and thrombocytosis." (PMID 16277681, 2005). "Laboratory investigations showed elevated thrombocytosis, CRP, ESR." (PMID 37848930, 2023). "Increased CRP and thrombocytosis reflect chronic active inflammation in this cohort." (PMID 35093127, 2022). "Furthermore, laboratory parameters, including leucocytosis (p = 0.014), thrombocytosis (p = 0.023), elevated CRP (p < 0.001), and CEA (p = 0.001) were statistically significantly different between the pCR and non-pCR groups." (PMID 36551723, 2022). "In addition, laboratory findings, such as thrombocytosis, C-reactive protein (CRP), and some stool markers, i.e., fecal calprotectin, are useful screening tests to assess the disease." (PMID 34066229, 2021). "However, IL-6 levels have been reported to correlate significantly with other markers of verified prognostic impact for MPM such as VEGF, thrombocytosis and CRP levels." (PMID 33562138, 2021). "During hospitalization 5 males developed mild thrombocytosis (median number of PLTs: 607 × 103/uL; range of values: 496–663 × 103/uL) and an increase in inflammation measured in terms of high CRP levels (median of values: 2.55 mg/dL; range of values: 1.07–4.61 mg/dL)." (PMID 33858472, 2021). "In addition to CRP induction, interleukin-6 also plays a pivotal role in thrombocytosis of inflammation." (PMID 32429293, 2020). "Additionally, although elevated plasma C-reactive protein (CRP) levels and thrombocytosis are strongly correlated and both indicate a poor prognosis for RCC patients, the bridge connecting inflammation and coagulation remains poorly understood." (PMID 31263677, 2019). "NLR and other similar indicators, such as C-reactive protein, albumin, the Glasgow prognostic score, thrombocytosis and PLR may reflect systemic inflammation." (PMID 28392554, 2017). "Two days later, as the symptoms persisted, laboratory tests disclosed an inflammatory syndrome including a hyperleukocytosis (25,060 white blood cells/mm3) with a majority of neutrophilic leukocytes, a thrombocytosis and an increased level of C-Reactive protein (CRP) at 109 mg/L." (PMID 25158781, 2014). "Three inflammatory markers were significantly associated with cancer-specific survival, with the pooled hazard ratio of 3.46 (95% CI 2.80 ~ 4.27) for elevated CRP, 3.22 (95% CI 2.25 ~ 4.62) for thrombocytosis, and 3.85 (95% CI 3.31 ~ 4.48) for elevated erythrocyte sedimentation rate (ESR)." (PMID 24877032, 2014). "Moreover, we found that PLT but not CRP was related to longer hospital stay, in accordance with report from EMBARC registry that thrombocytosis, but not CRP was associated with greater disease severity and increased hospitalization at 1 year." (PMID 38408986, 2024). "Besides, Platelets count and C-reactive protein, which may be referred to as thrombocytosis and inflammation marker in body, were also beyond normal range." (PMID 34126969, 2021). "Investigations showed elevated CRP (132 mg/L), ESR (49 mm/hour), WBC count (24.9 × 103/μL), ALT (33 IU/L), and thrombocytosis (893 × 103/μL)." (PMID 40161185, 2025). "Lab results showing microcytic hypochromic anemia, with normal leukocytes, eosinophilia, and thrombocytosis with elevated ESR and CRP." (PMID 39867099, 2024). "Initial lab workup showed microcytic hypochromic anemia, with normal leukocytes, eosinophilia, and thrombocytosis with elevated ESR and CRP." (PMID 39867099, 2024). "Severe RA correlates with thrombocytosis, hypergammaglobulinemia and elevated ESR and CRP levels in parallel with plasma and synovial levels of IL-6." (PMID 35886067, 2022). "Five of the rules generated using the DRSA method with the most clinical significance were based on following parameters: fair general condition, fever lasting ≥ 5 days, rash, conjunctivitis, CRP and ESR thrombocytosis." (PMID 34682194, 2021).
Thrombocytosis (continued). "Characteristic abnormalities are high levels of C-reactive protein (CRP), high erythrocyte sedimentation rates (ESR), neutrophilia, thrombocytosis, and hypochromic normo- or microcytic anemia." (PMID 26610523, 2015). "Laboratory examinations revealed thrombocytosis (511000/mm3), erythrocyte sedimentation rate (ESR) of 79 mm, and C-reactive protein (CRP) of 9.24 mg/dL, with normal hepatic and renal function, as well as the remainder of blood count." (PMID 25525549, 2014). "Blood workup revealed normocytic anemia, thrombocytosis and increased erythrocyte sedimentation rate (ESR) (110 mm/h), C-reactive protein (CRP) (33 mg/L) and angiotensin converting enzyme (ACE) (74 units/L)." (PMID 25494723, 2014). "The present study was designed in an attempt to characterize the different thrombocytosis states by PLT size, other hemogram parameters, serum iron profile, and CRP levels." (PMID 22997499, 2012). "WBC, ESR, CRP and PCT values were higher in the tuberculosis patients with thrombocytosis compared to those with a normal platelet count (p < 0.0001)." (PMID 23114411, 2012). "WBC, ESR, CRP and PCT values were higher in the patients with thrombocytosis compared to those with a normal platelet count, while Hb was found lower in these patients." (PMID 23114411, 2012). "Higher WBC, ESR, CRP and PCT values as well as radiological advanced stage were more common in PTB patients with thrombocytosis compared to the patients with normal platelet count, whereas Hb was found lower in these patients." (PMID 23114411, 2012). "In our study we also found ESR, CRP, WBC and PCT values to be higher, and Hb value lower, in PTB patients with thrombocytosis than in those with a normal platelet count." (PMID 23114411, 2012). "Despite clinical and radiological recovery, inflammatory markers remained persistently elevated, including neutrophilic leucocytosis, thrombocytosis, and elevated C-reactive protein (CRP), without residual symptoms or objective evidence of infection." (PMID 42186495, 2026). "Diagnosis is primarily clinical, and laboratory findings include elevation of inflammatory markers such as C-reactive protein (CRP) and erythrocyte sedimentation rate (ESR) alongside hematologic changes like neutrophilia, thrombocytosis, and normocytic anemia from chronic inflammation." (PMID 40677452, 2025). "Conversely, more than 96% of participants reported routinely using serial CRP measurements rather than relying on hyperleukocytosis or thrombocytosis monitoring." (PMID 40397486, 2025). "Laboratory tests revealed mild thrombocytosis with no elevated C-reactive protein (CRP), fibrinogen, or erythrocyte sedimentation rate (ESR) levels." (PMID 39640142, 2024). "Although KD is a clinical diagnosis and laboratory investigations have a minimal role in the diagnosis, children may have elevated inflammatory markers like CRP and ESR, thrombocytosis, and neutrophilic leukocytosis." (PMID 39877780, 2024). "Investigations showed neutrophilic lymphocytosis, high titres of CRP and ESR and thrombocytosis." (PMID 36096831, 2022). "As a result of this and the lack of additional benefit found in the validation cohort, CRP was not incorporated within the PLT/ALP rule, however, further research into its association with thrombocytosis and cancer would be worthwhile." (PMID 35482741, 2022). "Pathological laboratory test results such as ESR, CRP and thrombocytosis did not correlate with clinical signs of inflammation such as swelling, redness, local warmth or fever." (PMID 26088861, 2015). "The clinical manifestations of MCD are largely driven by activation of the interleukin-6 (IL6) signaling cascade, which results in an acute phase reaction with elevated erythrocyte sedimentation rate, C-reactive protein (CRP), fibrinogen, thrombocytosis and hypergammaglobulinemia." (PMID 23372742, 2013).
Thrombocytosis (continued). "CRP increase (100% of patients, median 212 mg/l), increased PMN counts [n = 26, 74% of patients, including 20 (57%) and 6 (17%) patients with leukemoid reactions and PMN counts over 10 and 20 G/L, respectively], thrombocytosis [n = 17 (48%)], and inflammatory anemia [n = 33 (94%)]." (PMID 39754984, 2025). "However, the persistence of fever, progressive laboratory abnormalities, including markedly elevated CRP (132 mg/L), ESR (49 mm/hour), thrombocytosis (platelets: 893 × 103/μL), and the development of coronary artery dilatation on echocardiography confirmed the diagnosis of incomplete KD." (PMID 40161185, 2025). "In RCC patients, elevated plasma C-reactive protein (CRP) levels and thrombocytosis are strongly correlated with poor prognosis and recurrence, indicating that inflammation and hypercoagulability may be critical environmental components required for CTC survival in circulation." (PMID 31263677, 2019). "Increased CRP was significantly higher in IgAV with PSE compared to those without PSE (52.6 % vs. 41.1 %, p = 0.03), likewise, thrombocytosis (> 400.000 mm3) (43.8 % vs.35.1 %, p = 0.04)." (PMID 41518866, 2026). "Increased CRP was significantly higher in IgAV with PSE compared to without PSE (52.6 % vs. 41.1 %, p = 0.03), likewise thrombocytosis (> 400.000 mm3) (43.8 % vs. 35.1 %, p = 0.04)." (PMID 41518866, 2026). "The remaining two patients had isolated skull lesions which were also initially thought to be quiescent even though there was thrombocytosis, because they were asymptomatic and other inflammatory markers, such as ESR and CRP were not elevated." (PMID 32903429, 2020). "Many other markers of the acute phase reaction, including C-reactive protein (CRP), ferritin, and erythrocyte sedimentation rate (ESR), are also significantly elevated in patients with reactive as opposed to clonal thrombocytosis." (PMID 22084665, 2011).
dementia (259 papers, 2004 to 2026). Loss of intellectual abilities interfering with an individual's social and occupational functions. "Overall, our results support DNAm CRP as a marker of chronic inflammation that is strongly associated with brain neurodegeneration, cognitive decline, and dementia risk." (PMID 41274863, 2025). "Anthocyanin supplementation reduces CRP and cardiovascular disease biomarkers in individuals at risk of dementia, especially when there is increased inflammation at baseline." (PMID 40314845, 2025). "A one standard deviation (SD) increase in DNAm CRP was associated with a 28% increase [HR: 1.28; 95% CI: 1.11–1.48] in dementia risk after adjusting for age and sex (p = 0.0007)." (PMID 41274863, 2025). "We thoroughly examined moderation and stratified analyses for APOE genotype and CRP in the association between multimorbidity clusters and dementia and explored the various methodologies used to define and analyse these clusters." (PMID 40990184, 2025). "Leveraging two external cohorts, we subsequently found DNAm CRP was associated with 18‐ and 25‐year dementia risk, whereas the results were mixed for DNAm GDF15." (PMID 41274863, 2025). "Compared to plasma levels of CRP, DNAm CRP appeared to show a stronger association with brain atrophy, cognitive decline, and dementia risk." (PMID 41274863, 2025). "Compared to plasma CRP, DNAm CRP was more strongly associated with brain volume, cognitive trajectories, and dementia risk." (PMID 41274863, 2025). "On the other hand, dementia risk was unrelated to plasma CRP (HR: 0.92; 95% CI: 0.75–1.12; p = 0.38) after age and sex adjustment." (PMID 41274863, 2025). "These signatures, especially DNAm CRP, were associated with accelerated brain atrophy, cognitive decline, as well as long‐term dementia risk." (PMID 41274863, 2025). "Elevated CRP and IL-6 levels are consistently associated with stress-perception phenotypes, cognitive impairment, and progression to dementia in vulnerable individuals, particularly when combined with pain and emotional stress." (PMID 41373439, 2025). "A one standard deviation increase in DNAm CRP was associated with a 19% increase [HR: 1.19; 95% CI: 1.08–1.31] in dementia risk after adjusting for age and sex (p = 0.0003)." (PMID 41274863, 2025). "In a 2-year longitudinal study of patients with CI, Gelin Xu and colleagues observed that elevated plasma CRP levels were associated with accelerated cognitive decline and an increased risk of dementia." (PMID 39819254, 2025). "Lastly, in a fully adjusted model, we found that 1 standard deviation above the mean log-transformed CRP was associated with 1.06 (95%CI: 0.99, 1.14) times greater risk of dementia in the overall sample." (PMID 39003383, 2024). "For only 2 risk factors (mother’s history of dementia, low C-reactive protein), their associations with incident all-cause dementia were stronger in APOE4 carriers." (PMID 38378514, 2024). "Sensitivity analyses 1 and 4 demonstrated that the significant association between health-risk behaviours and subsequent dementia status persisted after adjusting for baseline CRP levels and dementia, respectively." (PMID 38706574, 2024). "The EpiScore for CRP was also found to associate with time-to-dementia in the GS mixed effects model with basic adjustments (HR 1.35, PFDR < 0.05)." (PMID 38528588, 2024). "Our moderation analysis demonstrated that a mother’s history of dementia and low levels of C-reactive protein were more important risk factors of dementia in APOE4 carriers than in non-APOE4 carriers." (PMID 38378514, 2024). "For only 2 risk factors (mother’s history of dementia and C-reactive protein), their associations with incident dementia were stronger in APOE4 carriers than in non-APOE4 carriers.." (PMID 38378514, 2024). "For example, a study of more than 1000 people found that higher levels of the inflammatory marker C-reactive protein (CRP) were associated with a higher risk of developing cognitive impairment and dementia." (PMID 38540996, 2024).
dementia (continued). "The majority of risk factors showed a consistent effect on the risk of dementia and its subtypes, with one significant exception: a high level of C-reactive protein." (PMID 39335481, 2024). "Altogether, these results indicate that systemic inflammation is associated with dementia risk, and the effect of high CRP on dementia is moderated by minoritized group status." (PMID 39003383, 2024). "Our analysis has several strengths, including quantifying the association between CRP and incident dementia in a large (n = 6908) and diverse sample of older adults in the United States." (PMID 39003383, 2024). "While some data point to higher levels of CRP predict the progression of normal cognition to dementia, the relationship between CRP and dementia risk seems to be moderated by the presence of APOE4 carriership." (PMID 39358806, 2024). "This is in line with the results of a recent meta-analysis of 13 studies showing a robust association between elevated levels of pro-inflammatory markers such as CRP and α1-antichymotrypsin and all-cause dementia." (PMID 38706574, 2024). "Multivariable-adjusted ORs for all-cause dementia and for AD prevalence increased significantly with increasing serum hs-CRP levels (p for trend < 0.001 and p = 0.001, respectively)." (PMID 38548879, 2024). "The most recent meta-analysis confirmed these prospective links, demonstrating that the risk of all-cause dementia was increased by elevated CRP levels across eight longitudinal studies." (PMID 38706574, 2024). "The association between high CRP levels and incident dementia differed across minoritized and racialized groups." (PMID 39003383, 2024). "The HR (95% CI) for dementia associated with C-reactive protein (quintile 1 versus quintile 5) was 1.02 (0.88–1.18) in non-APOE4 carriers and 1.39 (1.23–1.57) in APOE4 carriers (P-value for interaction = 0.0001)." (PMID 38378514, 2024). "A meta-analysis including 28 observational studies found that biomarkers associated with dementia, such as elevated blood-based levels of IL-6, C-reactive protein, S100B, and NfL, were also associated with delirium." (PMID 37550780, 2023). "Further, one meta-analysis found that C-reactive protein level was associated with the risk of dementia, while another study found an association between IL-6 level and the risk of dementia." (PMID 37480061, 2023). "In this meta-analysis both the association between chronic inflammatory diseases and elevated levels of CRP during midlife were investigated to examine if they correlated with an augmented risk of dementia." (PMID 36776896, 2023). "The meta-analysis investigating levels of CRP and rates of dementia displayed that the risk of developing dementia was statistically significantly higher with elevated serum levels of CRP." (PMID 36776896, 2023). "Respondents in the 4th CRP quartile had a 1.148 higher risk of having dementia than those in the reference quartile (p = 0.006)." (PMID 37467176, 2023). "Within the APOE ε4 group, increased levels of CRP were associated with increased risk of AD and dementia." (PMID 37467176, 2023). "In the Framingham Heart Study (FHS), chronic peripheral inflammation measured with CRP increased the risk for dementia and AD dementia but only in apolipoprotein E (APOE) ε4 carriers." (PMID 37584418, 2023). "For instance, greater systemic levels of IL-6 and C-reactive protein (CRP) were found to associate with poorer cognitive performance and increased risk of dementia." (PMID 36915108, 2023). "Several observational studies have evaluated the associations between plasma CRP levels and risk of dementia, and the results were inconclusive." (PMID 38071240, 2023). "Our analysis has several strengths, including quantifying the association between CRP and incident dementia in a large (n = 5,143) large and diverse sample of older adults in the United States." (PMID 37066239, 2023).